MIR2278 (microRNA 2278)
Synonyms: hsa-mir-2278; mir-2278
Gene: MicroRNA gene on chromosome 9 (94,809,962 to 94,810,057, forward strand). Ensembl gene ENSG00000252153.
Diseases named in the same sentence as MIR2278 in open-access papers:
MIR2278 is named in the same sentence as 2 diseases in open-access papers, as found by Europe PMC text mining. Sharing a sentence is not in itself a finding about the gene and the disease. The quoted sentences say what the papers report.
nephrotic syndrome (1 paper, 2023). A collection of symptoms that include severe edema, proteinuria, and hypoalbuminemia; it is indicative of renal dysfunction. "Group 1 was characterized by major risk genes for developing LOAD (APOC1 and APOC1P1) and immune-related genes (RELB and CBLC), whereas group 2 was characterized by genes associated with kidney disorders, such as nephrotic syndrome (AXDND1, FBP1, and MIR2278)." (PMID 37386009, 2023).
kidney disorder (1 paper, 2023). A disease involving the kidney. "On the other hand, three of the four representative genes in group 2 (AXDND1, FBP1, and MIR2278) are likely to be associated with kidney diseases." (PMID 37386009, 2023). "The other was characterized by genes associated with kidney disorders (AXDND1, FBP1, and MIR2278)." (PMID 37386009, 2023).